SNORA50A (small nucleolar RNA, H/ACA box 50A)
Synonyms: ACA50; formerly SNORA50; SNORA76A
Gene: Small nucleolar RNA gene on chromosome 16 (58,559,796 to 58,559,929, reverse strand). Ensembl gene ENSG00000206952.
Gene Ontology:
Biological process: RNA processing
Cellular component: nucleolus
Homologues: Orthologues: chimpanzee SNORA50A (100% identical), macaque SNORA50A (100% identical), guinea pig SNORA50A (99% identical), rabbit SNORA50A (99% identical), pig SNORA50A (99% identical), mouse Gm26265 (96% identical). Paralogues in human: SNORA50B (63% identical), SNORA50C (56% identical), SNORA50D (53% identical).